MUC2 (mucin 2, oligomeric mucus/gel-forming)
Diseases named in the same sentence as MUC2 in open-access papers (continued):
Sharing a sentence is not in itself a finding about the gene and the disease.
colon carcinoma (continued). "Most importantly, inverse expression of the MUC2 and IL-6 proteins was observed in patients with stage II colon cancer." (PMID 28725043, 2017). "We examined the effects of MUC2 on colon cancer metastasis and used vector-mediated application of short hairpin RNA (shRNA) to suppress MUC2 expression." (PMID 28725043, 2017). "To further confirm the function of MUC2 in cancer metastasis, we examined the changes in liver metastasis induced by intrasplenic injection of colon cancer cells in immunocompetent BALB/c mice." (PMID 28725043, 2017). "Our results demonstrate that MUC2 downregulation and IL-6 overexpression correlate with human colon cancer metastasis." (PMID 28725043, 2017). "The objective of this study was to examine the signaling pathways mediated by the interaction between MUC2 and IL-6 during colon cancer metastasis." (PMID 28725043, 2017). "Supplementation of physiological concentrations of butyrate has been shown to increase MUC2 gene expression and MUC2 secretion in both human healthy goblet cell line and colon cancer cell line." (PMID 29033938, 2017). "In the present study, we further demonstrate the effects of MUC2 on migration and metastasis in human colon cancer cells." (PMID 28725043, 2017). "Further prospective studies evaluating adjuvant chemotherapy in stages II and III colon cancer should include MUC2, MUC5AC, and MUC6 expression analysis for patient stratification." (PMID 27298226, 2016). "Goblet cells secrete a type of mucin (MUC2) that inhibits the development of colon cancer in mouse models." (PMID 26230607, 2015). "To study the role of MUC2 in colon cancer, we used shRNA to suppress the expression of MUC2 in the CT26 murine colon cancer cell line, which expresses high levels of MUC2." (PMID 25322805, 2014). "Increased MUC2 expression stimulates metastasis and decreased expression reduces metastasis of colon cancer cells." (PMID 24533081, 2014). "Since colon cancer is associated with a proinflammatory microenvironment and dysregulated MUC2 expression, the aim of this study was to characterize the effects of MUC2 gene expression in colon tumor progression using colonic cancer cells." (PMID 25322805, 2014). "In the present study, we examined the effects of MUC2 on tumor cell growth, IL-6 secretion and the immune response in colon cancer." (PMID 25322805, 2014). "Human colon carcinoma cell lines that differentiate along a mucin secreting (MUC2/MUC5AC) and/or enterocytic (DPPIV) lineages were maintained on inserts with or without a γ-secretase inhibitor (DBZ)." (PMID 23409082, 2013). "Effect of γ-secretase inhibition on Hath1/MUC2/P27Kip1 expression in human colonic carcinomas in primary culture." (PMID 23409082, 2013). "We have previously shown that LTC4 stimulation of CysLT2R induces differentiation in Caco-2 colon cancer cells, as measured by increased MUC-2 mRNA expression and increased activity of the brush border enzymes alkaline phosphatase and aminopeptidase N." (PMID 23829413, 2013). "In this work we addressed the following 4 questions: Does γ-secretase inhibition modify the differentiation pattern of colonic cancer cells that are constitutively committed to differentiate into mucus-secreting (MUC2, MUC5AC) or enterocytic cells?" (PMID 23409082, 2013). "In the present study, the effectiveness of HIPEC was seen to decrease when MUC2 protein expression was seen in colon cancer cells and, conversely, to increase when MUC2 protein expression was not seen." (PMID 22266876, 2012). "One study showed that the colon cancer cell line LSLiM6 secretes MUC2, which, when inoculated into mice, induced metastasis in the liver." (PMID 23056409, 2012). "HIPEC therapy is thought to be effective in prolonging survival in patients with peritoneal dissemination of colon cancer, and MUC2 expression is thought to be useful as an indicator to assess its effectiveness in colon cancer cells." (PMID 22266876, 2012).
colon carcinoma (continued). "Expression of MUC2 protein and outcome was investigated in the patients with peritoneal dissemination of colon cancer in the HIPEC group." (PMID 22266876, 2012). "Previous work has shown that BAs can stimulate mucin secretion in a human colon cell line and up-regulate Muc2 in human esophageal and colon carcinoma cells." (PMID 22162748, 2011). "Previous results have also shown that the PKC inducer PMA and bile acids increase MUC2 expression in colon carcinoma cell line, and that this is prevented by the PKC inhibitor, calphostin C." (PMID 19014523, 2008). "On the other hand, our results contradict reports where IL-4 treatment has been shown to elevate MUC2 levels by a MAPK pathway in human colon cancer cells." (PMID 16551361, 2006). "MUC2 plays an important role in IL-6 signaling during colon cancer metastasis." (PMID 40859234, 2025). "Furthermore, stimulation of the human colon cancer cell line LS174T with IL-4 alone increased MUC2 mRNA expression by approximately twofold, suggesting that cytokines can influence mucin production." (PMID 40944230, 2025). "Similarly, Amuc_1434, which is also derived from AmEVs, has been reported to enhance the adhesion of the colon cancer cell line LS174T that expresses high levels of mucin 2 (Muc2) and also facilitated the degradation of Muc2 in colon cancer cells." (PMID 40028328, 2025). "In human studies, Campylobacter jejuni infection of HT-29 human colon cancer cells significantly upregulates pro-apoptotic proteins Bax and Bid, downregulates anti-apoptotic protein Bcl-2, and reduces the expression of the goblet cell marker MUC2." (PMID 40969431, 2025). "Amuc_1434 also promotes the mutual adhesion of colon cancer cells with high Muc2 expression." (PMID 39741950, 2024). "Amuc_1434 binds with normal colon cells and degrades Muc2 secreted by colon cancer cells." (PMID 39741950, 2024). "Moreover, murine models have demonstrated that MUC2−/− mice allowed bacteria to contact with the intestinal epithelium, resulting in inflammation and colon cancer." (PMID 37265504, 2023). "Hence, these results also suggested that traditional detection of goblet cells in colon cancer tissue by morphology‐based H&E staining or immunohistochemical or immunofluorescence staining of MUC2 and other molecular markers has great limitations." (PMID 36349418, 2023). "Interestingly, treatment of HM3 colon cancer cells with DCA resulted in abnormal expression of MUC2 by positive multiple pathways." (PMID 37265504, 2023). "In particular, the lack of MUC2 has been related to colon cancer development in Muc2−/− deficient mice." (PMID 35082322, 2022). "The deletion of MUC2 stimulates tumor-associated macrophages to produce more IL-6, which leads to the increase of STAT3 signal transduction and epithelial mesenchymal transformation (EMT) by colon cancer cells." (PMID 35936008, 2022). "Therefore, the expression of Muc2 was a valuable evaluative indicator for colon cancer–related diseases." (PMID 31861919, 2019). "Muc2 overexpression could pass the production of mucous barrier, protect tumor cells (such as colon cancer) from recognition by anti–tumor immune effectors and contribute to a malignant phenotype." (PMID 31861919, 2019). "Significantly Amuc_1434* can degrade Muc2 of colon cancer cells." (PMID 31861919, 2019). "Our results showed that MUC2 expression was much reduced in Tn‐positive human colonic cancer tissues relative to normal tissues, suggesting that MUC2 may require mature O‐glycosylation for its proper expression and stability." (PMID 29999571, 2018). "MUC2 suppression enhanced IL-6 secretion and tumor growth in a colon cancer animal model." (PMID 28725043, 2017). "Our results indicate that analyzing MUC2 expression in stage II colon cancer patients might help identify those who would potentially benefit from targeted therapy." (PMID 28725043, 2017). "A mouse model of liver metastasis was used to examine the function of MUC2 in colon cancer." (PMID 28725043, 2017).
colon carcinoma (continued). "The MUC2 protein plays an important role in IL-6 signaling during colon cancer metastasis." (PMID 28725043, 2017). "Most importantly, MUC2 is a potential prognostic indicator for colon cancer." (PMID 28725043, 2017). "Furthermore, IL-4 contributes in MUC2 regulation in colon cancer and its addition to cancer cells increases MUC2 secretion through a MAP kinase pathway, leading to the so-called mucinous carcinomas." (PMID 28927416, 2017). "To determine whether MUC2 silencing increases IL-6 secretion in HT-29 colon cancer cells, we incubated HT-29-derived cell clones with MSs for 48 h and determined the IL-6 concentration in the resulting supernatants by ELISA." (PMID 28725043, 2017). "Downregulation of MUC2 and overexpression of IL-6 were found in colon cancer." (PMID 28725043, 2017). "Notably, LS174T cells present a “goblet cell-like” phenotype and produce MUC2 but also demonstrate an aberrant secretion of human gallbladder mucin and gastric MUC5AC often associated with colon cancer." (PMID 26973622, 2016). "Therefore, we employed RNA interference (RNAi) to suppress MUC2 expression in mouse colon carcinoma cells, and evaluated the effects of MUC2 suppression on IL-6 production and tumor growth." (PMID 25322805, 2014). "MUC2 silencing also increased interleukin (IL)-6 secretion by colon cancer cells." (PMID 25322805, 2014). "Interestingly, mucin 2 (MUC2) mRNA that was increased 14–fold in SSA/Ps by RNA-seq has been reported to be decreased in colon cancers arising from adenomatous polyps." (PMID 24533081, 2014). "Finally, using a method of short term culture of primary human colonic carcinoma, we examined the response pattern of the tumor cells in terms of Hath1, MUC2 and P27Kip1 mRNAs to DBZ." (PMID 23409082, 2013). "Thus, ATRA-enhanced MUC-2 expression in SW480 colon cancer cells is at least partly mediated through CysLT2R and RARα signaling." (PMID 23829413, 2013). "Increased MUC2 mRNA was noted by quantitative RT-PCR analysis in human colon cancer cell lines in response to a single stimulation with IL-4 (approximate two-fold increase in comparison to baseline), IL-13, and TNF-α (c.2.5-fold increase in MUC2 mRNA) via MAP kinase pathways." (PMID 21152122, 2010). "It was recently shown that bile acids induce MUC2 overexpression in human colon carcinoma cells." (PMID 16755296, 2006). "While mucosal sulfation was previously reported to be significantly reduced in patients with UC, it is unclear whether this reduction was due to lower sulfation or decreased MUC2 expression, as the latter has also been noted in patients with UC and colon cancer." (PMID 37463055, 2023). "Thus, MUC2 expression is a valuable prognostic indicator for colon cancer." (PMID 28725043, 2017). "Thus, MUC2 expression in colon cancer may play an important role in the IL6-dependent signaling pathway." (PMID 28725043, 2017). "Furthermore, given the effects of MUC2 on IL-6 secretion, its targeting may represent a potentially useful strategy to treat colonic carcinomas." (PMID 25322805, 2014). "Therefore, MUC2 expression by colon cancer cells alters IL-6 secretion." (PMID 25322805, 2014). "Interestingly Hath1, MUC2, P27kip1 are per se tumor suppressor candidates in the colon and are therefore candidates for coupling the arrest of proliferation to the differentiation of colon cancer cells." (PMID 23409082, 2013). "In addition, because urachal carcinoma is expressed immunohistochemically as a unique colonic epithelial epitope that mimics the immunochemical profile of colonic cancer, its presence could be further confirmed by means of MUC2." (PMID 23914849, 2013). "In the current study, we show that ATRA’s ability to induce MUC-2 expression in SW480 colon cancer cells might also involve CysLT2R signaling, as the effect can be reduced by either a CysLT2R inhibitor or by RARα siRNA alone or a combination of RARα and RARβ siRNA." (PMID 23829413, 2013).
colon carcinoma (continued). "Thus, it may be that MUC2 proteins, by being secreted on the surface of colon cancer cells, protect the cancer cells at least partially from the effects of chemotherapy, which is thought to be related to the effects of HIPEC in this study." (PMID 22266876, 2012). "The MUC2 protein directly mediates Chk2/STAT3/CREB/ATF-1 signaling and E-cadherin expression in colon cancer." (PMID 40859234, 2025). "The expression patterns of MUC2 and LGR5 differ between the colon cancer cell line (Caco-2 cells) and colon organoids, highlighting the limitations of using 2D cultures as a model for studying viral infection." (PMID 40836050, 2025). "Turicibacter was significantly positively correlated with colonic tumor numbers and TNF-α, but significantly negatively correlated with MUC2, ZO-1, and butyric acid." (PMID 39924893, 2025). "Other mucins, such as MUC1, MUC2 and MUC5AC, are rarely expressed in normal tissues but are expressed in the early stages of lung cancer, breast cancer, and colon cancer." (PMID 38702644, 2024). "When evaluating new biomarkers for colon cancer, MUC1, MUC2, MUC4, MUC5AC, and MUC6 are currently documented in the largest bodies of work regarding their role in the progression from normal colonic tissue to malignancy." (PMID 36900282, 2023). "Numerous studies analyzed the gene transcriptional levels of colon cancer patients and found key genes such as GLUT1, MUC2, Cyclooxygenase-2, etc. that are related to the prognosis of colon cancer." (PMID 36755247, 2023). "These DEGs, significantly altered in human colon cancer tissue (TCGA) (Supplemental S4), are ones with both emerging roles (SEC24D, ABCC3, ATGL2B, and PCK2) and established roles (MYC and MUC2) in colonic tumorigenesis." (PMID 34845203, 2021). "The immunohistochemical marker profile of these tumors is similar to that of colonic carcinomas (CK20+, CK7−, and mucin 2 positivity (MUC2+))." (PMID 32148475, 2020). "Amuc_1434* is identified as a member of the aspartic protease family through the action of inhibitor pepstatin A. Amuc_1434* promotes the adhesion of colon cancer cell line LS174T, which can highly express Muc2." (PMID 31861919, 2019). "We used immunohistochemistry to detect the protein expression of MUC2, IL-6, and CD68 in serial sections of colon cancer tissues." (PMID 28725043, 2017). "We determined the MUC2 and IL-6 expression levels in 102 patients with stage IIA colon cancer and their correlation with clinicopathologic characteristics." (PMID 28725043, 2017). "It has been reported that the LGG-derived protein p40 up-regulates Muc2 gene expression and increases mucus production through transactivation of EGFR/Akt signaling in LS174T human colon cancer cells." (PMID 25915861, 2015). "Among the markedly increased genes in SSA/Ps that have also been reported to be increased in colon cancer were REG4, AQP5, MUC2, TFF1, KLK10." (PMID 24533081, 2014). "Moreover, DCA induces mucin 2 (MUC2) expression and suppresses tumour invasion in gastric carcinomas, oesophageal adenocarcinoma, and colon carcinoma." (PMID 39568157, 2024). "Other mucins, such as MUC2, MUC4, and MUC5AC, can also be considered for designing a mucin-based panel for serum profiling or histopathological analysis of tissue biopsies for the screening of colon cancer." (PMID 36980526, 2023). "RELMβ enhances MUC2 and M1/MUC5AC gene expression in human colon cancer cells." (PMID 36691020, 2023). "Because FCGBP and MUC2 have highly similar domains, it is tempting to speculate that FCGBP plays a role in promoting the invasion and metastasis of colon cancer." (PMID 35936008, 2022). "MUC-2 is a major part of intestinal mucins and most often found in the small intestine and colon; decreased expression of MUC-2 has been reported in non-mucinous colonic cancer." (PMID 36648870, 2022).
colon carcinoma (continued). "mRNA analysis of CEACAM5, KLK6, and SLC35D3 improves the detection of tumor cells in lymph nodes from patients surgically treated for colon cancer, and, together with POSTN and MUC2, it further allows characterization of the tumor cells with respect to aggressiveness and the tumor cell environment." (PMID 34192710, 2021). "With the immunophenotyping of CSLC, the anti-CD133 antibody was found to be effective for isolating a population of colon cancer cells that retained the properties of stem cells (CSLC), while anti-cytokeratin 20 (CK20) and anti-Mucin-2 (MUC2) were specific epithelium colonic differenziation markers." (PMID 32927614, 2020). "This analysis identified downregulation of MUC2 and overexpression of IL-6 in colon cancer but not in normal colon tissue, and this expression pattern was correlated with poor survival of colon cancer patients." (PMID 28725043, 2017). "In addition, other reports demonstrated that RA induces expression of MUC2, a differentiation marker gene, in SW480 colon cancer cells." (PMID 27564706, 2016). "CT26 colon cancer cells were stably transfected with MUC2 siRNA (MUC2 RNAi) or a control construct containing a nonspecific sequence (scrambled RNAi)." (PMID 25322805, 2014). "Although MUC2 suppression did not affect the cell growth of colon cancer cells in vitro, MUC2 knockdown promoted tumor growth in an orthotopic colon cancer model in vivo." (PMID 25322805, 2014). "In addition, O. splanchnicus showed a significant positive correlation with MUC2, ZO-1, Claudin, and IL-10, and a significant negative correlation with colonic tumor numbers, tumor volumes, advanced colonic lesions, TNF-α, and IL-1β." (PMID 39924893, 2025). "For example, the differential expression of MUC2 in mucinous/nonmucinous adenocarcinoma, and left/right colon cancer may be an important clue for differential diagnosis." (PMID 32695780, 2020). "Thus, our Oncomine analysis of colon cancer identified downregulation of MUC2 and overexpression of IL-6 in colon cancer but not in normal colon tissue." (PMID 28725043, 2017). "However, the effects of MUC2 expression on IL-6 secretion by colon cancer cells have not been determined." (PMID 25322805, 2014). "Up to now the impact of γ-secretase inhibitors on the differentiation of colonic cancer cells has been evaluated only on the basis of MUC2 gene expression, without taking into account the fact that colonic cancer cells ectopically express the MUC5AC gastric mucin." (PMID 23409082, 2013). "Consequently it is possible that colonic cancer cells over-expressing MUC2 without the concomitant expression of P27Kip1 are relieved from the constraints of terminal differentiation and anchorage-dependent growth." (PMID 23409082, 2013). "In addition, the possible targeting factors of NOTCH3 and SMARCA4 in colon cancer cells were screened through RNA‐seq, and, for the first time, we identified that MUC5AC and MUC2 may be the targeted factors for the co‐regulation of NOTCH3 and SMARCA4 interaction." (PMID 35900231, 2022). "In the nonmucinous type of colon cancer, decreased MUC2 expression was found, and expression was found to be suppressed by the transcriptional factor caudal type homeobox 2 (CDX2), which may have been caused by the high methylation modification of the promoter of the MUC2 gene." (PMID 32695780, 2020). "However, the elevated MUC2 expression (positive vs. negative: OR = 1.64, 95% CI = 1.01–2.67, P = 0.04) and MUC5AC expression (positive vs. negative: OR = 1.97, 95% CI = 1.48–2.62, P < 0.00001) were associated with colon cancer." (PMID 31933627, 2019). "Though the relevance of the MEK-ERK and PI3K-AKT signaling pathways to MUC2 gene expression has been previously shown in colonic goblet cells and in colon cancer cells, the relevance of KRAS oncoprotein to MUC2 gene expression has not been directly assessed." (PMID 28640835, 2017).